PCSK9 (proprotein convertase subtilisin/kexin type 9)
Diseases named in the same sentence as PCSK9 in open-access papers (continued):
Sharing a sentence is not in itself a finding about the gene and the disease.
lung adenocarcinoma (8 papers, 2021 to 2024). A carcinoma that arises from the lung and is characterized by the presence of malignant glandular epithelial cells. "PCSK9 exhibits distinct expression in normal and tumor cells, and in in vitro studies of lung adenocarcinoma, inhibiting PCSK9 demonstrates anti-tumor activity." (PMID 38822303, 2024). "Experiments conducted with in vitro models of human lung adenocarcinoma cells illustrate that inhibiting PCSK9 induces apoptosis, demonstrating noteworthy anti-tumor activity." (PMID 38822303, 2024). "Studies on the effect of PCSK9 siRNA on lung adenocarcinoma showed that PCSK9 had a pro-apoptotic effect on tumor cells by activating caspase-3 and weakening the functions of XIAP and survivin (a protein that is involved in the division and inhibition of apoptosis)." (PMID 35323699, 2022). "It showed that the high expression of PCSK9 was related to poorer OS in patients with BLCA (P = 0.001), KIRC (P = 0.01), KIRP (P = 0.011), LIHC (P = 0.024), lung adenocarcinoma (LUAD) (P = 0.011) and skin cutaneous melanoma (SKCM) (P = 0.001)." (PMID 38600469, 2024).
xanthoma (8 papers, 2014 to 2026). A non-neoplastic disorder characterized by a localized collection of histiocytes containing lipid. "Although the index patient carried the homozygous loss-of-function mutation in PCSK9, she presented severe phenotypes such as an uncontrollable cholesterol level; several elbows, knees, and hip xanthomas; and aortic valve disease, which necessitated valve replacement surgery." (PMID 33732287, 2021). "LDL-C lowering by statins, PCSK9 inhibitors, and lipoprotein apheresis can reduce xanthomas in patients with FH." (PMID 39595952, 2024).
alcoholic liver diseases (7 papers, 2019 to 2025). A disorder caused by damage to the liver parenchyma due to alcohol consumption. "Therefore, somewhat unsurprisingly, several features associated with alcoholic liver disease are likely to influence the role of PCSK9 in cholesterol homeostasis and liver function." (PMID 35162992, 2022). "It should be noted that higher serum levels of PCSK9 have also been observed in more prevalent chronic liver diseases, such as hepatitis C virus infection, alcoholic liver disease, and MASLD1,16." (PMID 41271978, 2025). "Supporting PCSK9 deregulation upon chronic alcohol exposure, analysis of end-stage alcoholic liver disease patients identified reduced hepatic PCSK9 mRNA levels in comparison to healthy-liver controls." (PMID 35162992, 2022). "PCSK9 inhibition moreover was effective in a rodent model of alcoholic liver disease, and improved hepatic inflammation." (PMID 33461570, 2021). "Future clinical studies in individuals with alcoholic and non-alcoholic liver disease are needed to evaluate efficacy and safety of anti-PCSK9 treatments in ALD/AUD." (PMID 31748600, 2019). "In this study, one adverse effect was a rise in serum triglycerides and free fatty acids, highlighting that further studies investigating the role of PCSK9 in alcoholic liver disease are needed to clarify if PCSK9 inhibitors have the potential to improve alcoholic liver disease." (PMID 35162992, 2022). "Thereby, it was proposed that PCSK9 may directly trigger the inflammatory reactions in the pathogenesis of alcohol liver disease." (PMID 33123601, 2020). "Interestingly, in a recent study, significant elevation was found in PCSK9 and inflammatory factors in the rat model of alcohol liver disease, whereas there was a significant inhibition of inflammatory reaction after administration of anti-PCSK9 agents." (PMID 33123601, 2020).
aneurysm (7 papers, 2021 to 2025). Bulging or ballooning in an area of an artery secondary to arterial wall weakening. "In an animal study, strong PCSK9 expression, similar to that in humans, was confirmed in the aneurysm walls of an AAA model." (PMID 41247317, 2025). "PCSK9 is also involved in the pathogenesis of acute vascular injury, and the expression of PCSK9 is significantly increased in mouse aneurysms and human aortic dissection." (PMID 35720337, 2022). "Here we found that endothelial KLF11 expression was reduced in the ECs from human aneurysms and was time dependently decreased in the aneurysmal endothelium from both elastase- and Pcsk9/AngII-induced AAA mouse models." (PMID 33507881, 2021). "Using a porcine pancreatic elastase (PPE) infusion model of AAA in C57BL/6J mice, we investigated whether Pcsk9 null mice demonstrated attenuated aneurysm growth compared to their wild-type counterparts." (PMID 37845353, 2023). "PCSK9 expression has been found to be upregulated in fibroblasts located in the neck of AAA, contributing to the weakening of the aneurysm wall." (PMID 41247317, 2025). "Proprotein convertase subtilisin/kexin type 9 (PCSK9) inhibitors have been shown to prevent plaque formation; however, no study has reported that PCSK9 reduces aneurysm size." (PMID 41247317, 2025). "In the current GoF mutant PCSK9 experiments, AAV infection alone, with or without a HFD, exerted no recognizable influence on experimental aneurysm progression or characteristic pro-aneurysmal aortic pathologies." (PMID 34680067, 2021).
aortic stenosis (7 papers, 2022 to 2026). Aortic valve stenosis is a aortic valve disease caused by the incomplete opening of the aortic valve. "The mechanism is related to the loss of PCSK9 function, which is why PCSK9-i can lead to a reduction in the incidence and progression of aortic stenosis." (PMID 37834387, 2023). "With this underlying substantial evidence, the PCSK9 inhibitors (deliberated as monoclonal antibodies: alirocumab and evolocumab) are currently being examined as pharmacological routes to delay the progression of aortic stenosis." (PMID 35743402, 2022). "While PCSK9 inhibitors have already demonstrated cardiovascular event reduction and possibly reduce the incidence of aortic stenosis, RNA-based therapies offer a novel approach targeting the causal role of Lp(a) in these diseases." (PMID 40943088, 2025). "The Proprotein Convertase Subtilisin/Kexin type 9 inhibitors (PCSK9-i) could decrease the progression of aortic stenosis and the requirement for valve implantation." (PMID 37834387, 2023). "However, new clinical trials targeting Lp(a) or PCSK9 are showing promising results in reducing the severity of aortic stenosis." (PMID 35743402, 2022). "The PCSK9 inhibition might lower the calcification in aortic stenosis valves." (PMID 40870420, 2025). "Other pharmacological approaches, such as statins, ACE inhibitors, PCSK9 inhibitors, or DPP-4, have not demonstrated many benefits in aortic stenosis outcomes." (PMID 40870420, 2025).
chronic obstructive pulmonary disease (7 papers, 2019 to 2025). A chronic and progressive lung disorder characterized by the loss of elasticity of the bronchial tree and the air sacs, destruction of the air sacs wall, thickening of the bronchial wall, and mucous accumulation in the bronchial tree. "In a rat model of ischemia/reperfusion injury, PCSK9 inhibitor was shown to reduce cardiac arrhythmias, suggesting potential cardioprotective effects beyond lipid-lowering." (PMID 40779566, 2025). "The expression of PCSK9 transcripts was dramatically attenuated in AT II cells in pulmonary fibrosis (6 donors), pulmonary systemic sclerosis (5 donors), and chronic obstructive pulmonary disease (COPD) (18 donors) compared to healthy condition (4 donors)." (PMID 39138259, 2024). "However, PCSK9-GS was also associated with higher risk of hospitalization with chronic obstructive pulmonary disease [COPD: n = 6836; 1.38 (1.08–1.76); P = 0.0089] and with even higher risk of fatal exacerbations amongst individuals with pre-existing COPD [n = 730; 3.61 (1.71–7.60); P = 7.3 × 10−4]." (PMID 38198221, 2024). "PCSK9 levels are higher in Bronchoalveolar lavage fluid (BALF) of smokers with or without chronic obstructive pulmonary diseases (COPD) compared to BALF of nonsmokers." (PMID 39138259, 2024).
Autoimmunity (6 papers, 2022 to 2024). The occurrence of an immune reaction against the organism's own cells or tissues. "The pleiotropic effects of PCSK9, which are associated with inflammation and immunity, suggest that PCSK9 inhibitors could potentially serve as a therapy against inflammation and autoimmunity." (PMID 38416767, 2024). "We then evaluated if reduction of circulating cholesterol could impact CNS autoimmunity using anti-PCSK9 antibodies, a new generation of lowering-cholesterol drug." (PMID 35130916, 2022). "To further evaluate the role of lowering cholesterol levels in CNS autoimmunity, we asked whether anti-PCSK9 could alter immune cell activation in the periphery despite the absence of differences in the clinical scores." (PMID 35130916, 2022). "Therefore, any speculation on the relationship between plasma PCSK9 levels and parameters of inflammation, autoimmunity or disease activity in pSS would remain undefined based on our results." (PMID 37759784, 2023). "When compared with heterozygous keratinocyte cell lines, PCSK9 SNP rs662145 C > T homozygous cell lines expressed low levels of PCSK9 and high levels of IL36 cytokines, a family of cytokines induced by IL-17A in autoimmunity and inflammatory skin conditions." (PMID 35862195, 2022). "Therefore, PCSK9 inhibitors not only lower LDL-C, but also regulate inflammation and autoimmunity (Frostegård, 2021)." (PMID 35222026, 2022). "Therefore, PCSK9 inhibitors not only reduce LDL-C, but also modulate inflammation and autoimmunity." (PMID 35222026, 2022). "With regard to cell-mediated immunity and autoimmunity, VXX-401 was found to safely overcome immune tolerance without generating a targeted T-cell response against PCSK9 or chronic inflammation." (PMID 38216056, 2024).
cataract (6 papers, 2019 to 2025). Partial or complete opacity of the crystalline lens of one or both eyes that decreases visual acuity and eventually results in blindness. "Further careful analyses are warranted to find thebeneficiaries of PCSK9 inhibitors in patients at risk for NODM, cognitiveimpairments, and cataracts." (PMID 39076187, 2022). "We determined whether the incidence of cataracts was influenced by treatment with the PCSK9 inhibitor alirocumab versus placebo, and whether that incidence was affected by achieved LDL-C levels." (PMID 37328736, 2023). "PCSK9 inhibitors are a safe alternative to statins,do not induce NODM, HS, cognitive effects, and cataracts, and do not have DDIswith anti-HIV drugs." (PMID 39076187, 2022). "PCSK9 inhibitors can achieve lower LDL-C levels than statins, while no sideeffect leading to cataracts has been detected." (PMID 39076187, 2022).
coronary artery stenosis (6 papers, 2014 to 2025). "We aimed to develop a porcine model for obstructive coronary stenosis induced by bioresorbable stent (BRS) implantation in hypercholesterolemic proprotein convertase subtilisin/kexin-9 (PCSK9) minipigs." (PMID 40131655, 2025). "Implantation of BRS in transgenic hypercholesterolemic PCSK9 minipigs induced formation of obstructive coronary stenosis." (PMID 40131655, 2025). "Plasma PCSK9 was measured by ELISA in 645 angiographically defined controls (<30% coronary stenosis) and 3,273 cases of CAD (>50% stenosis in a major coronary artery) from the Ottawa Heart Genomics Study." (PMID 25180781, 2014). "The main findings of this study on implantation of BRS for inducing coronary stenosis in hypercholesterolemic PCSK9 minipigs were: 1) severe in-scaffold stenosis developed in PCSK9 minipigs implanted with any of the three BRS types during 6 months of follow-up." (PMID 40131655, 2025). "Serum Pcsk9 levels correlates with severity of coronary artery lesion in PMI patients and may serve as a biomarker for severity of coronary artery stenosis in this patient population, which may contribute to risk stratification." (PMID 34044829, 2021).
diabetic kidney disease (6 papers, 2019 to 2025). Progressive kidney disorder caused by vascular damage to the glomerular capillaries, in patients with diabetes mellitus. "In a Chinese cohort of 1,228 participants with type 2 diabetes mellitus, polymorphisms in ApoB and PCSK9 were associated with hypertension and diabetic kidney disease (DKD)." (PMID 41573461, 2025). "PCSK9 inhibitors increase the risk of diabetic nephropathy and diabetic neuropathy." (PMID 40225015, 2025). "Serum PCSK9 was significantly higher in subjects with diabetic kidney disease (p = 0.020) and in patients with a history of MACE (p = 0.043), whereas atherosclerotic vascular disease, nephropathy, and neuropathy did not affect PCSK9 levels." (PMID 37620933, 2023). "Median levels of PCSK9 were 259.8 ng/mL, being higher in women compared to men and increasing even more in the presence of a complication (e.g., diabetic kidney disease)." (PMID 37620933, 2023). "The use of PCSK9 as a potential biomarker to identify patients with diabetic nephropathy who could benefit from anti-PCSK9 strategies and inhibition of PCSK9 could become an important treatment target in patients with CKD." (PMID 31915710, 2019). "While one diabetic kidney disease study noted higher PCSK9 levels were linked to worse renal parameters (lower eGFR and higher albuminuria), overall PCSK9 has not demonstrated robust independent prognostic power for CKD progression when traditional risk factors (eGFR, proteinuria) are accounted for." (PMID 40868936, 2025). "Through MR analysis of these complications, we examined the effects of three common cholesterol-lowering drug targets (HMGCR, PCSK9, and NPC1L1) on three major diabetic microvascular complications: diabetic retinopathy, diabetic nephropathy, and diabetic neuropathy." (PMID 40225015, 2025).
ischemia (6 papers, 2020 to 2023). A hypoperfusion of the BLOOD through an organ or tissue caused by a PATHOLOGIC CONSTRICTION or obstruction of its BLOOD VESSELS, or an absence of BLOOD CIRCULATION. "Inhibition of PCSK9 can improve the cerebral infarct volume in rats with cerebral ischemia/reperfusion injury, improve the dysfunction caused by ischemia, and protect the nerve, and its mechanism may be related to the inhibition of nerve cell apoptosis and promotion of its proliferation." (PMID 35378805, 2022). "The results of echocardiography showed that LVEF (16.02 ± 6.8% vs. 35.14 ± 5.0%, P < 0.05) and LVFS (10.62 ± 4.09% vs. 18.01 ± 1.16%, P < 0.05) in the PCSK9−/− ischemia group were significantly higher than that in the WT ischemia group." (PMID 35832650, 2022). "In vivo, the expression of the TLR4/MyD88/NF-κB pathway was upregulated in the WT ischemia group and downregulated in the PCSK9−/− ischemia group." (PMID 35832650, 2022). "The ELISA analysis showed that the expression of PCSK9 in peripheral mouse blood was increased in the WT ischemia group compared to the control group and WT sham group (P < 0.05)." (PMID 35832650, 2022). "In our study, we established a tMCAO model in SD rats to observe the interventional effects of PCSK9 inhibitor on neurobehavioral scores and cerebral infarct volume after ischemia/reperfusion in SD rats." (PMID 35378805, 2022). "Masson staining was used to evaluate the extent of myocardial fibrosis and indicated that the collagen density in the infarcted area of the PCSK9−/− ischemia group was obviously decreased compared to the WT ischemia group (44.15 ± 8.38% vs. 25.32 ± 3.23%, P < 0.05)." (PMID 35832650, 2022). "HE staining of myocardial tissue showed that a large number of inflammatory cells infiltrated the WT ischemia group myocardium compared to the WT sham group, but the number of inflammatory cells decreased notably when PCSK9 expression was knocked down (13.6 ± 1.39% vs. 7.50 ± 0.81%, P < 0.05)." (PMID 35832650, 2022). "The results showed that the proportion of M2 macrophages was increased compared to the WT ischemia group (27.58 ± 0.97% vs. 43.34 ± 0.61%, P < 0.05), and the proportion of M1 macrophages was decreased in the PCSK9−/− ischemia group (45.32 ± 4.19% vs. 34.54 ± 2.95%, P < 0.05)." (PMID 35832650, 2022). "In addition, PCSK9 inhibitors have been shown to improve cardiac function in rats with acute I/R injury when applied prior to ischemia." (PMID 33169229, 2020).